INS (insulin)
Diseases named in the same sentence as INS in open-access papers (continued):
Sharing a sentence is not in itself a finding about the gene and the disease.
type 2 diabetes (continued). "It has been demonstrated that in Pima Indians, a lot of white blood cells ispredictive of declining insulin action, insulin secretion function, regarding the onset of diabetes type 2." (PMID 39132231, 2024). "Clinical studies report low HDL and ApoA-I levels increase type 2 diabetes risk, and infusion of HDL into people with type 2 diabetes has been found to decrease plasma glucose while simultaneously increasing plasma insulin." (PMID 39546458, 2024). "Exercise is often recommended by front‐line clinicians as a potent therapeutic treatment in people with type 2 diabetes, and it can improve insulin sensitivity." (PMID 38522033, 2024). "We aim to assess β-cell function and IR in patients with type 2 diabetes on insulin therapy by fasting C-peptide to glucose ratio (FCPGR), and triglyceride glucose (TyG) index respectively to support treatment plans." (PMID 39252700, 2024). "It is therefore conceivable that insulin, besides being the only treatment option for those with type 1 diabetes, will continue to play a prominent role in the management of type 2 diabetes." (PMID 38679644, 2024). "The studied population (obese patients with type 2 diabetes and poor glycaemic control despite high doses of insulin) is the one that needs the most careful approach." (PMID 38792590, 2024). "Insulin is essential for the survival of people with type 1 diabetes and for better management of people with type 2 diabetes." (PMID 39361609, 2024). "This insulin-stimulated potassium uptake has been shown to be preserved in individuals with type 2 diabetes, even when cellular glucose uptake is reduced." (PMID 39796574, 2024). "Among the possible mechanisms involved, increased oxidative stress in pancreatic beta-cells or decreased insulin production emerge from the literature in connection with type 2 diabetes development." (PMID 39192017, 2024). "The present study aims to evaluate the impact of the metabolic effects of empagliflozin on cardiac function in patients with type 2 diabetes as compared to insulin treatment titrated to the same level of glycemic control in a randomized cross-over design." (PMID 38184612, 2024). "Type 2 Diabetes is a metabolic disorder characterized by elevated blood glucose levels resulting from excessive dietary carbohydrate consumption and a reduction in insulin sensitivity." (PMID 39769483, 2024). "Insulin, which has a compensatory hypersecretion in the early stages of type 2 diabetes (in addition to the insulin resistance at receptors levels), has been shown to potentially stimulate cancer cell growth (hence acting as a growth factor)." (PMID 39336089, 2024). "Accrued evidence has related magnesium deficits with modifications in insulin sensitivity and incident type 2 diabetes (T2D)." (PMID 38398820, 2024). "One patient of group 1 with an established diagnosis of type 2 diabetes on a background insulin regimen experienced relevant deterioration of glucose control, which was managed by increasing the mean daily insulin dose." (PMID 38195966, 2024). "The only current therapies available for type 2 diabetes are mechanisms to control the levels of insulin production and effectiveness or reduction in glycemic load through pharmaceutical actions, exercise, and diet." (PMID 38337589, 2024). "Type 2 diabetes was present in 11 patients, 8 under insulin treatment; 15 patients had hypertension (88%), 11 had dyslipidemia (69%), and 9 had sleep apnea (56%)." (PMID 38805173, 2024). "In animal models, quercetin (a flavonoid) and lycopene (a carotenoid) significantly decreased standard assay CRP in insulin-resistant and type 2 diabetic rats, respectively." (PMID 38999806, 2024). "The reason behind this association is believed to be the excessive accumulation of body fat, which impairs the secretion of hormones responsible for transporting insulin into cells, leading to type 2 diabetes." (PMID 38313972, 2024).
type 2 diabetes (continued). "Sulfonylureas are used in type 2 diabetes to enhance endogenous insulin secretion, especially in patients with residual beta-cell function." (PMID 39594624, 2024). "We also consider emerging indications for closed-loop systems, including the treatment of type 2 diabetes where variability of day-to-day insulin requirements is high, and other challenging applications for this technology." (PMID 38740602, 2024). "The first phase of insulin secretion is frequently used in pathophysiological studies of type 2 diabetes and the prediction of type 1 diabetes." (PMID 39013634, 2024). "Previous reports have shown that IMP is significantly increased in patients with type 2 diabetes and impairs glucose tolerance and insulin signaling when administered to mice, suggesting that it acts as a negative regulator." (PMID 38533495, 2024). "The results of this work are important because patients with type 2 diabetes have an inadequate insulin response after a meal, leading to challenges in glucose regulation." (PMID 38930808, 2024). "The continuous strain on insulin-producing cells eventually leads to diminished insulin production, indicating the transition from prediabetes to type 2 diabetes." (PMID 38791732, 2024). "For instance, in Korean subjects who underwent an oral glucose tolerance test, impairment in early-phase insulin secretion, assessed via the insulinogenic index, was suggested as the initial abnormality leading to type 2 diabetes." (PMID 39436903, 2024). "The current therapeutic strategies involve insulin replacement therapy for type 1 diabetes (T1D) and small-molecule drugs for type 2 diabetes (T2D)." (PMID 38540730, 2024). "The results of GSEA suggested that the ENPP3 was enriched in Toll like receptor signaling pathway and natural killer cell mediated cytotoxicity, NUDT12 was enriched in maturity onset diabetes of the young and insulin signaling pathway." (PMID 38464965, 2024). "Long‐term HFD feeding leads to type 2 diabetes symptoms including obesity, hyperglycemia, hyperlipidemia, and impaired insulin sensitivity in mice." (PMID 39512839, 2024). "When used in type 2 diabetes, the ketogenic diet results in reductions in glucose and insulin concentrations in serum, an improvement in HbA1c, and a reduction in the HOMA-IR (an indicator of insulin resistance)." (PMID 39519472, 2024). "We found that miR-10a/b-5p induces the growth of ICC and pancreatic β cells by targeting KLF11 (a causative gene for maturity-onset of diabetes of the young), which negatively regulates expression of KIT and insulin (INS) genes." (PMID 38396943, 2024). "In type 2 diabetes (T2D), environmental factors such as malnutrition or obesity impair insulin function, accelerating the depletion of islet β-cells." (PMID 39279997, 2024). "Although they reported Probiotics improved HbA1c and fasting insulin in people with type 2 diabetes, the reduction in HOMA-IR in intervention group compared to placebo was not significant." (PMID 38167029, 2024). "For example, intensive insulin therapy in patients with newly diagnosed type 2 diabetes has been shown to achieve long-term remission in approximately 50% of cases." (PMID 39560873, 2024). "Histomorphometry studies have shown older bone with reduced bone turnover and abnormal collagen structure in insulin-requiring women with type 2 diabetes." (PMID 38761257, 2024). "On the other hand, plant proteins promote insulin sensitivity and improved glycemic control in patients with type 2 diabetes." (PMID 38257161, 2024). "Current guidelines suggest CGM as a therapy strategy only in individuals with type 2 diabetes who use insulin." (PMID 38363342, 2024). "Liraglutide was also evaluated in terms of efficacy and safety in older adult patients with type 2 diabetes with insulin therapy." (PMID 39514148, 2024).
type 2 diabetes (continued). "Type 2 diabetes mellitus (T2D) is a complex chronic disorder that results from the dysregulation of lipids, protein, and carbohydrate metabolism, resulting in impaired insulin secretion and insulin resistance." (PMID 38612483, 2024). "Type 2 diabetes, characterized by inadequate insulin secretion and resistance, is increasingly prevalent." (PMID 38805166, 2024). "Most utilized cross-sectional and retrospective studies, relatively small sample sizes, did not consider associated factors over longitudinal data, and some were conducted only in patients with type 2 diabetes on insulin regimens." (PMID 39633380, 2024). "In the context of PCOS, elevated insulin levels stemming from IR can further complicate metabolic issues, such as obesity and type 2 diabetes, and aggravate PCOS symptoms by promoting increased androgen production." (PMID 38610028, 2024). "In terms of metabolic health, Mg has been shown to enhance insulin sensitivity, thereby playing a protective role against type 2 diabetes." (PMID 39539878, 2024). "In experimental models of obesity and type 2 diabetes, the authors showed positive effects on metabolic parameters, such as insulin signaling, after the use of GAL." (PMID 39204159, 2024). "This systematic review and network meta-analysis aimed to evaluate the effect of the two most advanced once-weekly insulin analogues, namely insulin icodec and insulin Fc, in patients with type 2 diabetes." (PMID 38172995, 2024). "Type 2 diabetes is characterized initially by impaired insulin sensitivity and subsequently by an inadequate compensatory insulin response." (PMID 39839287, 2024). "With a continued discrepancy between insulin requirement and insulin production, there is a rise in glycemic levels up to those consistent with type 2 diabetes." (PMID 39768947, 2024). "While type 1 diabetes must be treated with insulin replacement, type 2 diabetes can be treated with various oral and injectable medications and lifestyle modifications." (PMID 39105031, 2024). "Patients with type 2 diabetes are treated with insulin when oral hypoglycemic drugs are ineffective." (PMID 38884020, 2024). "This study aimed to evaluate the efficacy of pioglitazone, a strong insulin sensitizer with anti-inflammatory properties, in improving the clinical outcomes of patients with type 2 diabetes admitted with moderate–severe COVID-19." (PMID 39308871, 2024). "For people aged < 65 years with type 2 diabetes and on intensive insulin therapy, HbA1c reduction was significantly greater in those using CGM for 6 months compared to SMBG, with less time spent in hypoglycaemia, and improved quality of life." (PMID 39030640, 2024). "Systemic levels of TNF-a, IL-1b, IL-6, and CRP are elevated in both type 1 and type 2 diabetes patients, which is a result of the chronic activation of pro-inflammatory pathways within insulin-target cells." (PMID 38904046, 2024). "Preliminary findings indicate that the myokine profile of primary skeletal muscle cells from patients with Type 2 diabetes mellitus (T2DM) differs from that of insulin-sensitive individuals." (PMID 39640300, 2024). "The normalization of both pancreatic beta cell function and hepatic insulin sensitivity in type 2 diabetes was achieved by dietary energy restriction alone, despite that all oral antidiabetic agents or insulins had been stopped at baseline." (PMID 38791525, 2024). "Agonists of PPARγ, such as thiazolidinediones (e.g., pioglitazone, rosiglitazone), enhance insulin sensitivity and regulate glucose metabolism, making them effective treatments for type 2 diabetes." (PMID 39458951, 2024). "Effective self-management of patients with type 2 diabetes (T2D) can be achieved by applying the correct technique for insulin use." (PMID 39337195, 2024). "Insulin plays a central role in regulating blood glucose levels, and impaired insulin signaling in muscle and adipose tissue is a known contributor to type 2 diabetes." (PMID 39906036, 2024).
type 2 diabetes (continued). "Here, we review the current knowledge on β-cell hypoxia, focusing on impaired insulin secretion in type 2 diabetes." (PMID 38673770, 2024). "Our data stress the importance of taking into consideration differences in the secretion and clearance of insulin between groups when investigating the aetiology of postprandial hyperinsulinaemia in obese and type 2 diabetes populations." (PMID 39138690, 2024). "Adults with either type 1 diabetes or type 2 diabetes requiring intensive insulin therapy participated at four sites in South Korea." (PMID 38133642, 2024). "Type 2 diabetes exhibits a heterogeneous nature, characterized by the interplay of defects in both insulin secretion and action." (PMID 39072261, 2024). "Pharmaceutical treatments that are used to treat type 2 diabetes include insulin sensitizers, insulin-promoting agents, α-glucosidase inhibitors, incretin-based therapies, and sodium-glucose co-transporter 2 inhibitors." (PMID 39590850, 2024). "Previous work has shown that loci within the GLIS3 gene region have a shared effect on both T1D and type 2 diabetes risks via effects on pancreatic β-cell function, insulin sensitivity and inflammation." (PMID 39263363, 2024). "For any CHIP, DNMT3A CHIP, TET2 CHIP, and ASXL1 CHIP, the top outcomes reflected CpG sites related to age/aging, alcohol consumption, smoking, and multiple CVD-related traits including body mass index (BMI), type II diabetes, and fasting insulin." (PMID 39070619, 2024). "Type 2 diabetes is an endocrine disorder characterized by compromised insulin sensitivity that eventually leads to overt disease." (PMID 38880916, 2024). "Skeletal muscle is the major tissue responsible for insulin-stimulated glucose disposal and muscle insulin resistance is a critical component in the pathogenesis of type 2 diabetes." (PMID 38216792, 2024). "Type 2 diabetes is a metabolic condition to affecting hyperglycaemia and insulin production leading to resistance." (PMID 39204303, 2024). "When analysing the glycogen synthesis results, myotubes from two donors with type 2 diabetes showed a robust response (2.0- and 2.5-fold) to insulin stimulation (see Glucose metabolism, below)." (PMID 38814443, 2024). "Our results are similar to previous systematic reviews and meta-analyses that have shown that once-weekly insulin is superior to once-daily insulin for glycemic control in terms of HbA1c in type 2 diabetes." (PMID 39629047, 2024). "High levels of these mediators are also found in patients with type 2 diabetes, subsequently triggering impaired insulin sensitivity and glucose homeostasis." (PMID 39518420, 2024). "The increase in Rdins in the Obese-NGT and type 2 diabetes groups was attributable to the greater hepatic delivery of insulin (i.e. during the first and second pass) compared with Lean-NGT." (PMID 39138690, 2024). "This study developed and validated the effectiveness of a pattern management educational program using CGM to improve self-care and physiological indices in type 2 diabetics receiving insulin therapy." (PMID 39057524, 2024). "Bioactive peptides regulate type 2 diabetes by influencing enzymes in carbohydrates metabolism, insulin secretion, and incretin hormones such as GIP and GLP-1, thereby impacting postprandial blood glucose levels." (PMID 39330503, 2024). "Because chronic hyperglycemia in people with type 2 diabetes increases the demand for insulin, the β-cells become increasingly overworked." (PMID 38398503, 2024). "In the final experiment, we analysed serum samples from patients with type 2 diabetes who received five weekly doses of insulin icodec." (PMID 39033137, 2024). "In adults with type 2 diabetes under multiple daily insulin injections (MDI), isCGM has been observed to improve glycated haemoglobin (HbA1c), with reductions in hypoglycaemia and increased treatment satisfaction." (PMID 38337336, 2024).
type 2 diabetes (continued). "Metformin (MTF), an indirect mTOR kinase inhibitor, is a widely recognized oral medication commonly used to manage type 2 diabetes by improving insulin sensitivity and reducing blood sugar levels." (PMID 38797976, 2024). "In another study from 2020, chokeberry extract given to rats with type 2 diabetes resulted in lower blood glucose and insulin levels." (PMID 38929138, 2024). "Additional mechanistic studies would be useful to identify the different roles of BCAAs, insulin, and type 2 diabetes and hence targets of intervention." (PMID 38459184, 2024). "Our aim was to conduct a systematic review of randomized controlled trials that investigated the effectiveness and safety of once-weekly insulin in individuals with type 2 diabetes." (PMID 38172995, 2024). "Future investigations should consider employing higher dosages of cafestol to elucidate its effects on insulin sensitivity and other cardiometabolic parameters in prediabetic and type 2 diabetes subjects." (PMID 39408200, 2024). "Impaired lipid signaling and insulin sensitivity can contribute to metabolic syndrome, hypertension, and type 2 diabetes." (PMID 39717856, 2024). "Diabetes is a chronic disease, and insulin treatment is life-saving for all people with type 1 diabetes and many with type 2 diabetes, having unmatched glucose-lowering capability." (PMID 39033137, 2024). "Insulin dysregulation is a key feature of type 2 diabetes that interferes with the insulin signaling pathways and has been identified as a risk factor for the development and progression of various types of cancer." (PMID 38272982, 2024). "For example, engineered insulin plays a crucial role in type II diabetes with a longer effect than own insulin." (PMID 38716460, 2024). "In the Lean-NGT group, there was an immediate post-meal increase in insulin clearance compared with pre-meal values (p<0.05), whereas insulin clearance remained stable at baseline values in Obese-NGT or declined slightly in the type 2 diabetes group (p<0.05)." (PMID 39138690, 2024). "In human association studies, SNPs in the SSPN locus had strong associations with increased waist-to-hip ratio (WHR), fasting insulin adjusted for body mass index (FIadjBMI), and type 2 diabetes." (PMID 39120469, 2024). "Potential mechanisms include elevated human ACE2 in type 2 diabetes patients, coupled with reduced insulin secretion and induced pancreatic β cell apoptosis due to SARS-CoV-2 infection." (PMID 39144619, 2024). "While the majority of patients with type 2 diabetes initially start with oral hypoglycemic drugs, eventually many will need insulin therapy." (PMID 39629047, 2024). "Metformin is a first line oral antidiabetic drug that improves cellular insulin sensitivity in insulin-resistant individuals, especially those with type 2 diabetes." (PMID 38541119, 2024). "When type 2 diabetes is treated with insulin, many of these people are able to maintain good glycaemic control with just intermediate or long-acting insulin." (PMID 38654804, 2024). "It has been shown to mitigate insulin dependency in individuals with type 2 diabetes by promoting glucose transferinto cells and triggering Adenosine monophosphate-activated protein kinase (AMPK)." (PMID 39309571, 2024). "Different from type 2 diabetes, the earliest pathogenesis of type 3c diabetes secondary to chronic pancreatitis is insufficient insulin secretion." (PMID 39839287, 2024). "(Male, Moroccan) (As of July 1st2023 continuous glucose sensor (GCS) monitoring use is being reimbursed in Belgium for type 2 diabetes on an intensive insulin regimen (i." (PMID 39541382, 2024). "Since FLCs are byproducts of antibody production, circulating FLCs have been postulated to act as a biomarker of chronic inflammation in patients with type 2 diabetes, and a potential surrogate measure of insulin sensitivity." (PMID 38725572, 2024).